NRG1 (neuregulin 1)
Diseases named in the same sentence as NRG1 in open-access papers (continued):
Sharing a sentence is not in itself a finding about the gene and the disease.
schizophrenia (continued). "Here, we describe the expression of Nrg1 mRNA across postnatal life in two schizophrenia-relevant brain regions that express high levels of Nrg1." (PMID 25992564, 2015). "The leading Nrg1 mouse studied in the context of a ‘schizophrenia’ model is the heterozygous transmembrane domain (Nrg1 TM HET) mouse, which is implied to be a hemizygous ‘knockout’ model of reduced Nrg1 function." (PMID 25992564, 2015). "While cognitive and social deficits and the altered response to psychosocial stress overlap as endophenotypes for schizophrenia and depression, there is much less research examining NRG1-KO mice in the specific context of depression." (PMID 25762938, 2015). "An association between neuregulin 1 (NRG1) and schizophrenia is strongly supported by human genetic studies." (PMID 25762938, 2015). "Cell-specific gene modification techniques are now starting to elucidate a link between Nrg1/ErbB4 signaling and pathophysiology of schizophrenia." (PMID 25805966, 2015). "Neuregulin-1 and DISC1 signalling pathways have both been linked to neurodevelopment and schizophrenia." (PMID 26656849, 2015). "In specific, Study C found a significant over-representation of GG homozygotes among schizophrenia patients at SNP8NRG241930 in NRG1 (P<0.001)." (PMID 26199897, 2015). "So far, research findings emphasise that Nrg1-ErbB4 mouse models are useful tools in schizophrenia research, including gain-of-function models for Nrg1 but further investigation and integration of various approaches is required." (PMID 25992564, 2015). "One of the most consistent pathologies in the cortex of patients with schizophrenia involves GABAergic interneurons, which are dependent on NRG1-ErbB4 signaling for maturation." (PMID 25992564, 2015). "Neuregulin 1 (NRG1) and the γ-secretase subunit APH1B have been previously implicated as genetic risk factors for schizophrenia and schizophrenia relevant deficits have been observed in rodent models with loss of function mutations in either gene." (PMID 24891237, 2014). "Nrg1 confers vulnerability to the effects of environmental challenges of relevance to schizophrenia." (PMID 25324742, 2014). "In a discordant monozygotic twins study, the twin with schizophrenia also displayed lower NRG1-stimulated AKT phosphorylation." (PMID 25688191, 2014). "Neuregulin 1 (NRG1), a leading schizophrenia susceptibility gene, is relevant to several schizophrenia-related neurodevelopmental processes." (PMID 24904437, 2014). "The use of genetically modified mice that carry a truncated TMc domain-Nrg1 gene as an experimental tool offers an alternative model with which to mimic a NRG1 deficiency in some schizophrenic patients and to test a NRG1 loss-of-function hypothesis for schizophrenia." (PMID 24782733, 2014). "We obtained DNA from 31 patients with schizophrenia and 23 healthy controls and analyzed NRG1 rs6994992, NRG1 rs3924999 and NRG3 rs10748842 promoter polymorphisms by allelic discrimination with real-time polymerase chain reaction (PCR)." (PMID 24976857, 2014). "Manipulation of NRG1 and ErbB4 in rodents leads to behavioral and neurophysiological phenotypes relevant to schizophrenia, consistent with their known roles in neuronal development, myelination and neurotransmitter function." (PMID 25093331, 2014). "The sex-specific alterations of cognitive function observed in our male TMc-Nrg1+/−mutant mice are somewhat consistent with the gender-specific differences in patients with schizophrenia." (PMID 24782733, 2014). "In 2002, DeCode Genetics Inc. reported a genetic association of the NRG1 gene with schizophrenia and our group found abnormal expression of EGF and ErbB1 in the postmortem brains of patients with schizophrenia." (PMID 24949465, 2014). "In conclusion, our study sheds light on the physiological role of Aph1b-γ-secretase in brain and provides a new mechanistic perspective on the relevance of NRG1 processing in schizophrenia." (PMID 24891237, 2014).
schizophrenia (continued). "Heterozygous deletion of NRG1 results in increased sensitivity of mice to schizophrenia-like symptoms induced by THC especially under stressful conditions." (PMID 24904437, 2014). "Studies investigating the link between NRG1 and schizophrenia have demonstrated that NRG1 has a functional effect on the immune system by influencing immune cell adhesion and the concentration of autoantibodies and pro-inflammatory cytokines in plasma." (PMID 25919455, 2014). "Because the transmembrane domain of NRG1 is vital for both forward and reverse signaling cascades, new Nrg1-deficient mice that carry a truncation of the transmembrane domain of the Nrg1 gene were characterized and used in this study to test a NRG1 loss-of-function hypothesis for schizophrenia." (PMID 24782733, 2014). "More importantly, it provides unique insight into the importance of Nrg1 intracellular signalling in the establishment of functional synapses and the potential aetiological role of misprocessing of NRG1 in the pathogenesis of schizophrenia." (PMID 24891237, 2014). "Moreover, putative loss of function variants of APH1B, a crucial component of the γ-secretase complex, were found to aggregate with NRG1 risk alleles in schizophrenia patients and Aph1b-loss of function mutations in rodents display behavioural phenotypes that are relevant for schizophrenia." (PMID 24891237, 2014). "Our data illustrate the interaction between two signaling pathways (BDNF and NRG1), which are well studied for their roles in synaptic plasticity and in the pathophysiology of many neuropsychiatric disorders including schizophrenia." (PMID 25052836, 2014). "Suggested candidate genes include, but are not limited to, neuregulin 1 (NRG1), disrupted in schizophrenia-1 (DISC1), and catechol-1-methyltransferase (COMT)." (PMID 24674381, 2014). "Mouse models of both enhanced and reduced NRG1-ERBB signally display a variety of schizophrenia related behaviors." (PMID 25505409, 2014). "For example, in a complex disorder such as schizophrenia, it has been consistently reported that several specific signaling molecules, including AKT, DISC1, NRG1 and calcineurin, are associated with the disease." (PMID 25290670, 2014). "A number of Nrg1-related mutant mice have been generated to further elucidate the role of Nrg1 in the pathogenesis of schizophrenia-related behavioral and cognitive deficits." (PMID 24782733, 2014). "Although the underlying mechanisms require further investigation, our data suggest that valproate has great potential for improving cognitive deficits in patients with schizophrenia, especially males with NRG1 haploinsufficiency." (PMID 24782733, 2014). "NRG1/ErbB-dependent signaling is involved in a multitude of biological functions that are key factors in schizophrenia pathophysiology." (PMID 24683514, 2014). "The neighboring FC peak at chromosome 8p12 is located directly over NRG1 [GenBank:NG_012005] (0-LOD drop from peak), a known schizophrenia risk gene." (PMID 24533643, 2014). "Evidence revealing the link between Nrg1/ErbB4 and cognitive deficits in patients with schizophrenia has begun to accumulate." (PMID 24782733, 2014). "Accumulating evidence indicated that AKT1 and NRG1 were involved in social functions of schizophrenia." (PMID 25688191, 2014). "Based on NRG1's established role in schizophrenia and the availability of validated mouse mutants for Nrg1, we investigated over the last decade if Nrg1 represents a second candidate for gene-cannabis interactions in schizophrenia." (PMID 23447438, 2013). "The human NRG1 gene has been linked to schizophrenia by genetic studies and altered expression of NRG1 isoforms has been measured in schizophrenia patients." (PMID 23447498, 2013). "In an initial study we exposed Nrg1 HET mice to acute doses of THC before testing them in an array of schizophrenia-relevant behavioral paradigms." (PMID 23447438, 2013).
schizophrenia (continued). "The mini review will outline how our mouse research has been instrumental in discovering Nrg1-cannabis interactions relevant to schizophrenia and in deciphering potential mechanisms." (PMID 23447438, 2013). "In adolescence Nrg1 modulated the effects of repeated THC exposure on the expression of neurotransmitter receptors relevant to the pathophysiology of schizophrenia (i.e., CB1, NMDA, and 5-HT2A receptors)." (PMID 23447498, 2013). "Peripheral blood microarray findings have implicated sensory and motor neuron derived factor (SMDF), a splice variant of NRG1, in patients with schizophrenia." (PMID 23805071, 2013). "We have shown Nrg1 HET mice display distinct schizophrenia-relevant neurobehavioral responses to cannabinoids, including the main psychoactive constituent of cannabis, Δ9-tetrahydrocannabinol (THC)." (PMID 23447498, 2013). "Nrg1 modulated the behavioral sensitivity of mice to cannabinoids differentially during adolescence and adulthood providing evidence for a role of Nrg1-cannabis interactions in schizophrenia." (PMID 23447438, 2013). "Mice that are hypomorphic for Nrg1 (Nrg1 HET mice) display schizophrenia-relevant behavioral phenotypes and aberrant expression of serotonin and glutamate receptors." (PMID 23447498, 2013). "It should be noted that sex-specificity in rodent models for Nrg1 is a common phenomenon and is in line with gender effects reported for schizophrenia patients." (PMID 23966917, 2013). "Reduced expression of NRG1 has also been observed in PBMCs from first-onset schizophrenia patients compared to controls, which normalized following treatment with antipsychotic medications." (PMID 23805071, 2013). "More evidence suggests that ErbB4 exerts its effects on PV-positive interneurons: PV-ErbB4-/- mice exhibit a schizophrenia-like phenotype much like that of NRG1-null and ErbB4-null mutants; these mice are hyperactive and show impaired working memory." (PMID 23618463, 2013). "Here we review the effects of cannabinoids on a mutant mouse model for the schizophrenia candidate gene neuregulin 1 (Nrg1)." (PMID 23447438, 2013). "This mini review will focus on recent advancements in the field made by challenging mutant and transgenic rodent models for the schizophrenia candidate gene neuregulin 1 (NRG1) with particular environmental factors." (PMID 23966917, 2013). "As described in the introduction, the polymorphisms of NRG1 and PTK2B are associated with schizophrenia, respectively." (PMID 23555897, 2013). "Genetic manipulation of schizophrenia susceptibility genes in rodents, such as DISC1, NRG1/ErbB4, and COMT has been largely explored as well." (PMID 24027504, 2013). "The possible mechanisms by which altered function of NRG1 and its receptor ErbB4 contribute to schizophrenia have been reviewed by Mei and Xiong." (PMID 23618463, 2013). "Four articles discuss the animal model of schizophrenia, two of which address the Nrg1-cannabinoid interaction in a hypomorphic Nrg1 (Nrg1 HET) mouse model of schizophrenia." (PMID 24348332, 2013). "On the other side, stress impacted positively on the hyper-locomotive phenotype of Nrg1 mutant mice, outlining the complexity of GxE interactions in schizophrenia and the need to look at specific disease endophenotypes." (PMID 23966917, 2013). "Many studies investigated the genetic association of NRG1 and ERBB4 with a risk of developing schizophrenia in various ethnic groups." (PMID 23301017, 2013). "These brain areas are important in schizophrenia and are characterized by high expression levels of Nrg1, its main receptor ErbB4 and CB1." (PMID 23447438, 2013). "Recent association studies have revealed genomic regions of NRG1 and ERBB4, which are significantly associated with risk of developing schizophrenia; however, inconsistencies exist in terms of validation of findings between distinct populations." (PMID 23301017, 2013).
schizophrenia (continued). "Three widely reported schizophrenia susceptibility genes, disrupted in schizophrenia 1 (DISC1), neuregulin 1, and dysbindin, have been shown to regulate new neuron development in adult brain." (PMID 22697179, 2012). "EGR3 is also a target gene for Brain-derived neurotrophic factor (BDNF) and Neuregulin 1 (NRG1), both of which are schizophrenia susceptibility genes." (PMID 22276163, 2012). "Mice hypomorphic for NRG1 or ErbB4 show behavioral abnormalities consistent with existing animal models for schizophrenia, including abnormal prepulse inhibition and enhanced response to cannabinoid and dopaminergic agonists." (PMID 22028923, 2011). "This interpretation is functionally consistent with the genetic association of NRG1 and ERBB4 with schizophrenia." (PMID 22087295, 2011). "Neuregulin 1 (NRG1) is the most well characterized member of the family, and Nrg1 is also a leading schizophrenia susceptibility gene." (PMID 21949880, 2011). "This is the first time thatsupportive evidence shows an involvement of the NRG1 locus in schizophrenia in anIranian sample population." (PMID 23508206, 2011). "Our preceding study suggests that neuregulin-1, another ErbB receptor ligand, also induce several behavioral abnormalities relevant to schizophrenia, when neuregulin-1 is administered to newborn mice." (PMID 22022452, 2011). "Of the transgenic animal models, the NRG1-erbB4 transgenic mouse seems to have more similarities to observations in patients with schizophrenia, while relatively few studies have been done in the other two genetic animal models." (PMID 22937274, 2011). "Changes in the expression levels of EGF, NRG1 and ErbBs are also found in postmortem brains and peripheral blood of schizophrenia patients." (PMID 22022452, 2011). "In the functional studies, mutant mice heterozygous for either NRG1 or its receptor erbB4 showed a behavioral phenotype that overlaps with mouse models for schizophrenia." (PMID 22937274, 2011). "Single nucleotide polymorphisms (SNPs) in the genes encoding Neuregulin-1 (NRG1) and its receptor ErbB4 are associated with increased risk for and endophenotypes of schizophrenia; NRG1 is also associated with bipolar disorder." (PMID 22087295, 2011). "In this report, we investigate theassociation of the SNP8NRG241930 polymorphismof NRG1, located at the 5' end of this gene,with schizophrenia in a homogenous populationcity of Ahwaz, southwestern, Iran." (PMID 23508206, 2011). "NRG1 has been studied as a candidate gene forseveral diseases such as: schizophrenia, bipolardisorder (BPD), multiple sclerosis and cancer." (PMID 23508206, 2011). "More interestingly, the behavioral phenotypes of the NRG1 hypomorphs were partially reversible with clozapine, an atypical antipsychotic drug used to treat schizophrenia." (PMID 22937274, 2011). "In particular, Type III Nrg1 back signaling can acutely activate PtdIns3K along sensory neuron axons making TRPV1 a potential molecular link between Type III Nrg1, schizophrenia and alterations in pain sensation." (PMID 21949864, 2011). "(χ2: 16.09, p≤0.001).This result indicated positive evidence for theassociation of NRG1 with schizophrenia in oursamples." (PMID 23508206, 2011). "Many model studies have used NRG1 hypomorphic mutant mice to study the phenotypic consequences of decreased NRG1 signaling as well as its pathologic contribution to schizophrenia." (PMID 21151609, 2010). "Using this cell system, we found that NRG1-stimulated cell adhesion and migration were impaired in patients with schizophrenia." (PMID 20520724, 2010). "A genetic association between the neuregulin-1 (NRG1) gene and schizophrenia has been documented in various human populations." (PMID 21151609, 2010). "These phenotypic abnormalities of NRG1 knockout mice are in agreement with the neuropathological findings on postmortem brains of schizophrenia patients." (PMID 21151609, 2010).
schizophrenia (continued). "We assessed behavioral pathology of adult NRG1-Tg mice by measuring locomotor activity, prepulse inhibition (PPI), fear learning, and social interaction, which are often implicated in schizophrenia animal models." (PMID 21151609, 2010). "The animal and patient studies suggest that decreased NRG1 signals are responsible for the pathophysiology of schizophrenia." (PMID 21151609, 2010). "We have previously reported that NRG1-stimulated migration of B lymphoblasts is PI3K-AKT1dependent and impaired in patients with schizophrenia and significantly linked to the catechol-o-methyltransferase (COMT) Val108/158Met functional polymorphism." (PMID 20520724, 2010). "NRG1 exists in multiple isoforms, and two independent studies have shown that the type I isoform is selectively increased in schizophrenia and the recently described type IV isoform has also been implicated." (PMID 19457239, 2009). "NRG1 remains one of the more convincing genes to show genetic linkage to schizophrenia in multiple studies, albeit with a small effect size." (PMID 19457239, 2009). "ERBB3 (v-erb-b2 erythroblastic leukemia viral oncogene homolog 3), encoding a receptor of neuregulin-1 (NRG1), has been considered a functional candidate gene for schizophrenia susceptibility." (PMID 21637446, 2009). "NRG1-ErbB signaling regulates oligodendrocyte development and myelination and abnormalities in oligodendroglia and myelin are reported in schizophrenia." (PMID 18335055, 2008). "For example, mice with mutations in Neuregulin-1, Disrupted in schizophrenia 1 (DISC1) and calcineurin, all identified as risk genes for schizophrenia, show impaired working memory." (PMID 18945333, 2008). "Overall, our studies show that NRG1 signaling activates adhesion machinery in a process that is impaired in cells derived from patients with schizophrenia." (PMID 18159252, 2007). "A novel Neuregulin 1 (NRG1) missense variant (exon 11 G>T) was recently associated with psychosis and schizophrenia (SCZ) in the same population isolate." (PMID 17519028, 2007). "Expanding the analysis to include additional schizophrenia-associated genes such as DISC1, NRG1, COMT, and DTNBP1 could provide a more comprehensive view of the genetic risk factors relevant to our population." (PMID 40977746, 2025). "Similarly, schizophrenia has been associated with mutations in genes governing synaptic function and neurodevelopment, such as the DISC1 and NRG1 genes." (PMID 40282331, 2025). "Notably, miR-382-5p has also been shown to target NRG1 in spinal cord injury and its involvement extends to the pathogenesis of various neurological disorders, including migraine, schizophrenia, and cerebral ischemia–reperfusion injury." (PMID 40192890, 2025). "Furthermore, investigations have highlighted the involvement of Akt signaling in the operations of genes linked to schizophrenia vulnerability, including DISC-1, NRG-1 and dysbindin-1." (PMID 41283305, 2025). "Although the role of neuregulin 1 in schizophrenia is strongly related to complex alterations with an impact on plasticity and its regulating role in excitatory/inhibitory synapses, especially in the prefrontal cortex, little is known about its role in treatment response." (PMID 39062492, 2024). "Thus, NRG1 through the ErbB4 receptor plays a crucial role in the complex processes of learning and memory, impacting the synaptic plasticity in schizophrenia, which accounts for cognitive deficits, emotion dysregulation, and impaired global functioning." (PMID 39062492, 2024). "Furthermore, NRG-1 knockout mice showed schizophrenia-related behavioral deficits that were less responsive to amelioration by olanzapine than similar behavioral deficits induced by MK801." (PMID 39334950, 2024). "Although pharmacogenetic markers related to schizophrenia and clinical outcomes of antipsychotic treatment are areas of intense study, relatively few data are available on risperidone monotherapy in relation to both COMT and NRG1 polymorphisms." (PMID 39062492, 2024).